IL1R1 (interleukin 1 receptor type 1)
Diseases named in the same sentence as IL1R1 in open-access papers (continued):
Sharing a sentence is not in itself a finding about the gene and the disease.
tumor (continued). "In addition, the tumour size of B16F10-IL-1β- and B16F10-vector tumours was similar in Il1r1−/− mice, indicating that the inhibiting effect of tumour-derived IL-1β on tumour growth was dependent on the host response." (PMID 23065753, 2012). "However, the effect of tumour-derived IL-1β on neutrophil infiltration was completely abolished in Il1r1−/− mice." (PMID 23065753, 2012). "Similarly, in subcutaneous PDAC models, mice treated with anti-IL-1R1 antibodies showed accelerated tumor growth compared with the untreated group, and treatment with the combination of anti-IL-1R1 and agonistic CD40 antibodies performed worse than agonistic CD40 antibody monotherapy." (PMID 40060615, 2025). "The results related to interleukins indicated that IL1R1 gene expression was higher in the A3 and A5 than in other cell lines indicating that such gene expression increased in response to radiation in the early stages of cell transformation and influenced tumor formation in this experimental model." (PMID 39201290, 2024). "Finally, we showed that the KRAS blocker deltarasin acts to downregulate IL1R1 (interleukin-1 receptor 1) expression in KRAS-mutant tumor cells and that the proposed KRAS/CCL2/IL1B signature is enriched in human cancers with high KRAS mutation frequencies, in which it portends a dismal prognosis." (PMID 35327394, 2022). "However, IL-1R1 deletion in colonic epithelial cells reduced the tumor number." (PMID 33578830, 2021). "Indeed, lack of Il1r1 in neutrophils promotes tumor-associated dysbiosis, with a consequently heightened infiltration of bacteria into the tumor tissue, increased production of pro-tumorigenic cytokines by TAMs, and aggressive CRC progression." (PMID 32962159, 2020). "Interestingly, the pro-inflammatory cytokine IL-1B and its receptor IL1R1 were increased in bone metastases compared with primary tumours in ER+ BB2RC08 cells but appeared to decrease in ER-ve BB6RC37 cells, and similar pattern was observed with the cell-cell adhesion molecule γ Catenin." (PMID 31783893, 2019). "In these particular genetic IL-1R1 knockdown experiments we used a much higher dose of cetuximab (6 mg/kg) than the cetuximab dose (2 mg/kg) utilized for the SQ20B-xenograft mouse models described in the main manuscript, which caused a complete inhibition of tumor growth." (PMID 30890189, 2019). "IL1R1 was positively correlated with regulating T cells CD4 and macrophages M2, implying that IL-1 signaling regulated tumor microenvironmental homeostasis and immune response through different immune cells." (PMID 40535567, 2025). "Conversely, a negative correlation was observed between the production of interleukin 1 alpha (IL1A) by CAFs and the expression of its receptors—IL1R1, IL1R2, and IL1RAP—on tumor cells." (PMID 39519201, 2024). "CAFs are a relevant cell population in the PDAC stroma that express IL-1R1, and when stimulated with IL-1α and/or IL-1β, they secrete several pro-tumor cytokines, including TSLP, which is responsible for pro-tumor Th2 inflammation in PDAC." (PMID 39125655, 2024). "We found that the xenograft tumours from HT1080-LT cells had higher mean telomere length than those from HT1080 cells and had lower IL1R1 expression at the protein level." (PMID 39728924, 2024). "It was observed that TRF2 occupancy, as well as IL1R1 mRNA expression, was lower in HT1080-LT-derived xenograft tumours." (PMID 39728924, 2024). "Macrophages induce ROS elevation and increase expression of IL1α, which is bound to IL1R1 to activate ERK1/2, MKK4, and NF‐κB‐mediated signaling pathways to facilitate tumor growth and metastasis." (PMID 37551997, 2023). "IL1R1 is expressed in various types of cancer cells and CAF, which are stromal cells that support tumor growth and survival." (PMID 37207166, 2023). "Directly targeting these molecules especially IL1R1 and IL1RAP significantly impaired the survival and growth of KSHV+ tumor cells, as well as their colony formation on 3-D culture." (PMID 36457850, 2022).
tumor (continued). "Of note, compared with IL1R1− Treg cells or CD4+ T cells, IL1R1+ Treg cells expressed higher levels of CXCR6, which was recently reported to be critical for anti-tumour activity of cytotoxic T cells in a mouse model." (PMID 35545675, 2022). "We show that the co-expression of IL1R1 and ICOS uniquely identifies an intratumoural Treg population from all other haematopoietically-derived (CD45+) cells in the tumour or peripheral blood." (PMID 35545675, 2022). "The activity of IL-1R1, present in numerous TME cells, suggests the participation of IL-1 signaling in various stages of tumor development." (PMID 33557173, 2021). "Il1r1 was increased significantly in the early stage of tumor progression by PRI-2191 in young and by calcitriol in old mice, whereas in the late stage of tumor growth the level of its expression was increased by calcitriol and PRI-2191 only in young mice." (PMID 32257539, 2020). "Moreover, mature FOXP3+ Tregs in the tumor express CXCR6, IL21R, IL1R1, IL18R1, and, to a lesser extent, CCR8." (PMID 40164596, 2025). "Tumor‐related angiogenesis is inhibited if either IL‐1β or VEGF are neutralized, as IL‐1β and VEGF can work as an auto‐induction circuit and interact with bone marrow–derived VEGFR1+/IL‐1R1+ immature myeloid cells (MDSCs) and tissue‐resident endothelial cells." (PMID 40135589, 2025). "Chronic inflammation is a well-known enabling characteristic of cancer, and IL-1 signaling, primarily through IL-1R1, is a primary regulator of the inflammatory response within the tumor microenvironment (TME), where its activation promotes a vicious cycle of tumor growth and spread." (PMID 41415279, 2025). "Additionally, we performed mIF on tumor tissues from LACC patients, using antibodies against IL1R1, p16, and vimentin." (PMID 39903771, 2025). "The observed overexpression of IL1RAP and the substantial but similar expression levels of IL1R1 in tumor and adjacent non-neoplastic tissues further corroborate the significant role of IL-1 signaling in CRC." (PMID 38979413, 2024). "Collectively, we found that ANK-SNs did not have cytotoxic effects, were efficiently internalized through specific interaction at the cell surface with IL-1R1, and down-modulated the secretion by CAFs of TSLP, IL-8, IL-6, and TGF-β, thus dampening their tumor-promoting functions." (PMID 39125655, 2024). "TRF2-induced tumours had enhanced IL1R1 relative to the xenograft tumours where TRF2 was not induced." (PMID 39728924, 2024). "Similarly, pharmacological inhibition of IL-1β or IL-1R1 locally decreases intratumoral TAM content and prolongs survival of tumor-bearing mice." (PMID 37733448, 2023). "Tumor-infiltrating Treg cells selectively expressed IL1R1 receptors marked a highly suppressed and enlarged fraction of Treg cells and suppressed CD8 + T cells more efficiently in contrast to IL1R1-Treg." (PMID 37710294, 2023). "Silencing of Il1r1 in the lung significantly decreased pulmonary metastases of Hepa1-6 xenografts without affecting primary tumor growth." (PMID 37443052, 2023). "In addition, immunofluorescence staining of tumor histology samples from CRC patients revealed colocalization of PDPN, whose gene is part of the IL1R1+ iCAF set, and IL1R1 in the stromal tissue (lower-right panel for quantification)." (PMID 37460545, 2023). "This loop further interconnected IL1β with the expression of IL1R1 in luminal cancer cells MCF7 and SKBR3, fostering functional crosstalk between the tumor microenvironment and intracavitary breast cancer cells, consequently promoting tumor metastasis." (PMID 38001753, 2023). "Here, we showed how deltarasin functions to abrogate a mutant KRAS-initiated in vivo inflammatory loop of tumor-derived CCL2 and myeloid-secreted IL-1β by downregulating the IL1R1 expression of KRAS-mutant tumor cells and thereby abolishing their receptivity to myeloid IL-1β signals." (PMID 35327394, 2022).
tumor (continued). "Furthermore, while the inactivation of epithelial-specific IL-1R1 resulted in a decrease in CRC burden, a similar knockdown of IL-1R1 in myeloid cells enhanced tumor growth." (PMID 35884974, 2022). "In the current study, we found that many of IL1 signaling molecules (e.g., IL1α, IL1β, IL1R1, IL1RAP, IL36, IL36R and IRAKs) were highly activated during KSHV infection or in KSHV+ tumor cells and tissues, indicating the crucial role of these molecules functions in KSHV pathogenesis and oncogenesis." (PMID 36457850, 2022). "The absence of IL1R1 in T cells inhibits the production of IL‐17 and IL‐22, reducing the tumour‐induced inflammation, whereas in myeloid cells it increases the bacterial infiltration into the tumour tissue and triggers a pro‐tumorigenic inflammatory response." (PMID 36433652, 2022). "Yet, tumor cells produce TGF-β, which downregulates the expression of IL-1R1 on local CAFs." (PMID 36499246, 2022). "We found that IL1R1+ Treg cells were more effective than their IL1R1− counterparts at suppressing proliferation of CD8+ and CD4+ responder T (Tresp) cells isolated from tumours as well as from peripheral blood." (PMID 35545675, 2022). "The expression of IL1R1 in the tumor microenvironment, the main receptor of IL1α and β, due to the interconnection with the NF-KB and MAP kinase pathways, plays contrasting roles in different tumor stages." (PMID 34073987, 2021). "The increase in tumor-initiating ability and growth, mediated by cancer cells co-implanted with fibroblasts, was also observed using MDA-LM2 cells; however, this induction was significantly restrained when Il1r1−/− fibroblasts were co-implanted." (PMID 32198421, 2020). "Indeed, IL-1R1 deletion in myeloid cells resulted in increased inflammation and enhanced bacterial infiltration, thus boosting CRC tumor progression." (PMID 32825489, 2020). "We showed that IL-1 blockade using anakinra (which binds both human and mouse IL-1R1) did not significantly affect tumor response to cetuximab in Cal-27 and SQ20B xenograft tumors." (PMID 30890189, 2019). "Using the IL-1R1 knockdown SQ20B cells shown in Fig.S 1G-I in athymic nude mice, we showed that knocking down the IL-1R1 using both clones (shIL-1R#1 and shIL-1R#2) did not enhance but partially and significantly reversed the anti-tumor effect of cetuximab." (PMID 30890189, 2019). "We also treated tumour-bearing DIO mice with anakinra, a recombinant IL-1 receptor antagonist approved by FDA to treat other human diseases, and found a similar result as with anti-IL-1R1 antibody." (PMID 27708283, 2016). "Anti-IL-1R1-treated DIO mice had significantly reduced tumour growth compared with control IgG-treated DIO mice or non-treated DIO mice." (PMID 27708283, 2016). "IL1R1 and IL1RN expression varied widely in different tumors, suggesting that ligand-receptor-antagonist regulation may possess different equilibrium points in different tumor environments." (PMID 40535567, 2025). "This suggests that IL-1R1 might not act on hepatocyte cell death during tumor progression but during initiation or early tumor promotion." (PMID 39621069, 2024). "A previous study showed that higher expression levels of IL1R1 proteins were detected in GBM samples than in normal specimens by immunohistochemical experiments, which may have a meaningful impact on the prognosis of neoplasms." (PMID 37153540, 2023). "Similarly, we have previously found that inhibiting IL1R1 with Anakinra reduces subcutaneous tumour growth in BALB/c nude mice, but the same dose did not reduce primary tumour growth in NOD SCID mice." (PMID 36230739, 2022). "Our data showed that directly silencing of IL1 signaling molecules such as IL1R1 and IL1RAP significantly reduced the survival and growth of KSHV+ tumor cells, indicating targeting IL1 signaling may represent a promising strategy for treatment of KSHV-related malignancies." (PMID 36457850, 2022).
tumor (continued). "While the inhibitory receptor SIGIRR is shut down in tumor cells, the expression of the activatory IL1R1 is maintained (data not shown), and we next asked if SIGIRR downregulation may unleash intrinsic IL1 signaling in RCC cells." (PMID 35814450, 2022). "After addressing the role of stromal-derived IL-1B signalling by using parental E0771 in mice lacking IL-1B or IL1R1, next we investigated whether tumour-derived IL-1B rescues the lack of microenvironment-derived IL-1B." (PMID 34290237, 2021). "In these models, we found that inhibition of IL1R1 did not affect primary tumour growth, whereas inhibition of IL-1B resulted in increased primary tumour growth, therefore recapitulating the effect that we had previously seen following pharmacological inhibition of IL-1B signalling." (PMID 34290237, 2021). "Focusing on the functional interaction that occurs between tumor cells and the surrounding stroma, we also determined that IL-1β secreted by hypoxic TNBC cells may promote a feed-forward loop engaging its cognate receptor IL1R1 in breast CAFs." (PMID 32778144, 2020). "To further confirm the role of the IL1β-IL1R1 axis in activating the NF-κB pathway and inducing pro-inflammatory cytokine expression in TCM-treated SCs, we utilized two siRNAs against IL1B to knockdown IL1β levels in tumor cells, which was validated using ELISA." (PMID 32308766, 2020). "Based on tumor purity, we ascertained that most cytokines are secreted by TAMs and M2 macrophages, and marker sets have significant correlations with CDH11 in STAD, with examples including CCL-2, TGFB1, CXCL12, and MPP2 of TAMs and IL-10, IL1R1, CD163, and MRC1 of M2 phenotype (P < 0.0001)." (PMID 32685527, 2020). "Our study for the first time reports a role for the inflammatory marker, IL1R1 of the interleukin-1 family, in ST-EPN-RELA and PF-EPN-A molecular subsets of EPNs, with possible roles in regulation of EMT, stemness, angiogenesis, metabolism and tumor inflammatory responses." (PMID 30464804, 2018). "To determine whether the IL-1β module acts directly on the tumour cells, we silenced Il1r1 in Py8119 cells and found no impairment of tumour growth in DIO mice, indicating that IL-1β does not primarily act on cancer cells." (PMID 27708283, 2016). "IL-1β negative B16F10-vector tumours grew faster in wild-type mice than in Il1r1−/− mice, suggesting that IL-1β produced by inflammatory cells and stromal cells may promote tumour growth." (PMID 23065753, 2012). "Thus, hepatic activation of IL-1R1 due to nonresolving metabolic inflammation in MASLD may favor tumor development." (PMID 39621069, 2024). "We first tested whether the receptors predicted by NicheNet were present as proteins, and found that IL1R1 was expressed specifically by tumour-infiltrating Treg cells, but not by tumour-infiltrating CD4+ T cells or CD8+ T cells, nor by T cells in the peripheral blood." (PMID 35545675, 2022). "The genes Fam65b and Il1r1 were methylated preferentially in the non-tumor liver tissue, whereas the genes Synpo and Tspan9 were methylated preferentially in tumors; the gene Srd5a2 in each half of the tested tumors was preferentially methylated in either the non-tumor tissue or in tumors." (PMID 25918251, 2015). "Recent research has demonstrated that while the lack of IL-1R1-in epithelial cells lowers tumor incidence in APC models, the absence of IL-1R1-in neutrophils increases bacterial invasion and tumor invasiveness." (PMID 40868987, 2025). "Overall, these results showed that blocking the IL-1R1 signaling pathway in hepatocytes did not prevent malignant transformation and tumor formation in the DEN+HFD model but substantially suppressed tumor growth in obese mice at a later stage." (PMID 39621069, 2024). "In our data, we had observed consistent change in IL1R1 and IL1B in long versus short telomere tumours and also noted that IL1 signalling has been widely implicated with TAM infiltration in multiple cancers." (PMID 39728924, 2024).
tumor (continued). "Our data revealed that targeted knockout of IL-1R1 in hepatocytes did not protect mice from malignant transformation of liver cells in response to DEN and HFD feeding but significantly slowed tumor growth in steatotic livers." (PMID 39621069, 2024).